NARS2 (asparaginyl-tRNA synthetase 2, mitochondrial)
Diseases named in the same sentence as NARS2 in open-access papers (continued):
Sharing a sentence is not in itself a finding about the gene and the disease.
cerebral infarction (1 paper, 2025). An ischemic condition of the brain, producing a persistent focal neurological deficit in the area of distribution of the cerebral arteries. "In the present case, cerebral infarction was identified on MRI following status epilepticus, representing a previously unreported manifestation of NARS2-related COXPD24." (PMID 41426993, 2025). "Notably, cerebral infarction has not been previously reported in NARS2-related disorders, suggesting a potential expansion of the clinical spectrum." (PMID 41426993, 2025).
hyperglycaemia (1 paper, 2025). "Our study confirms NARS2 as an NDM etiological gene, which should be tested in neonates presenting with hyperglycaemia, especially if they are born to consanguineous unions and have neurological features." (PMID 40887432, 2025).
Mitochondrial myopathy (1 paper, 2021). "Among the patients whose biopsy was indicative of a mitochondrial myopathy, we reached seven genetic diagnoses including one case with mutation in mtDNA (T8993C), AGK (two cases), TSEN54 (one case), EARS (one case), TSFM (one case), and NARS2 (one case)." (PMID 34675869, 2021).
mitral valve prolapse (1 paper, 2024). A fairly common and often benign valvular heart disorder characterized by redundancy or hooding of mitral valve leaflets so that they prolapse into the left atrium, often causing mitral regurgitation. "Heart phenotype in patients with NARS2 deficiency was rare with mitral valve prolapse and cardiac dysfunction, while myocardial dysfunction has been reported in other aaRSs, including AARS2 and Lysyl-tRNA synthetase (KARS)." (PMID 38310242, 2024).
myoclonic seizures (1 paper, 2024). "Most of the patients with NARS2 variants had focal, generalized, or myoclonic seizures and mitochondrial abnormalities such as combined complexes decreased and structurally abnormal." (PMID 38310242, 2024).
ovarian carcinoma (1 paper, 2020). A malignant neoplasm originating from the surface ovarian epithelium. "In contrast, for ovarian cancer (OV), higher expression of NARS2 is favorable for survival." (PMID 33266490, 2020).
prostate carcinoma (1 paper, 2024). A carcinoma that arises from epithelial cells of the prostate gland. "Our study found that DNBs and four genes (SCD, NARS2, ALDH1A1, and NFXL1), as relevant factors associated with androgen-related signaling pathways in prostate cancer cells, can be further used as indicators of PCa progression after androgen deprivation therapy." (PMID 39335669, 2024). "Yet, few studies have demonstrated the role of NARS2 in prostate cancer." (PMID 39335669, 2024). "In addition, the WGCNA method was used to identify core genes, and when combined with DNBs, four genes including SCD, NARS2, ALDH1A1, and NFXL1 were found to be associated with androgen-related signaling pathways in prostate cancer cells." (PMID 39335669, 2024). "This may be one of the few studies to provide some evidence about the role of NARS2 in prostate cancer progression and yet, more in vivo analysis is needed to clarify the role of such a gene." (PMID 39335669, 2024).
seminoma (1 paper, 2025). A radiosensitive malignant germ cell tumor found in the testis (especially undescended), and extragonadal sites (anterior mediastinum and pineal gland). "Other TGCT susceptibility genes also appeared amongst the hub genes of modules in both the seminoma and non-seminoma modules, including NARS2 in the yellow(NS) module and G3BP2 in the lightyellow(SE) module." (PMID 39809819, 2025). "The TGCT susceptibility genes TEX14, NARS2, and G3BP2, were identified as hub genes in both seminoma and non-seminoma networks." (PMID 39809819, 2025).
Sensorineural hearing impairment (1 paper, 2021). A type of hearing impairment in one or both ears related to an abnormal functionality of the cochlear nerve. "More relevant is the sensorineural hearing impairment, as a hallmark of NARS2-associated LS phenotype, which is consistent with the proband’s symptoms." (PMID 35004675, 2021).
Sepsis (1 paper, 2024). Sepsis is defined as life-threatening organ dysfunction caused by a dysregulated host response to infection. "In addition, a homozygous missense variant in another recently described novel gene, NARS2, was identified in three probands who presented with ND, seizures, and sepsis." (PMID 40302952, 2024).
status epilepticus (1 paper, 2024). Status epilepticus is defined as a continuous seizure lasting more than 30 min, or two or more seizures without full recovery of consciousness between any of them. "We discovered two novel missense variants of NARS2 in a patient with early-onset status epilepticus and myocardial dysfunction." (PMID 38310242, 2024).
mitochondrial disease (4 papers, 2018 to 2025). "Variants in this gene have previously been reported to cause a mitochondrial disease, and only recently one report described two siblings presenting with ND and being compound heterozygous for variants in NARS2." (PMID 40302952, 2024). "Our findings provide new insights into NARS2-related mitochondrial disease, highlighting the importance of comprehensive genetic testing, early recognition of acute manifestations, and multidisciplinary management to improve outcomes in affected individuals." (PMID 41426993, 2025). "In this article, we present clinical and molecular findings of 219 patients with LS and give the detailed description of three cases with rare findings in nuclear genes MORC2, NARS2 and VPS13D, demonstrating wide genetic heterogeneity of this mitochondrial disease." (PMID 36675121, 2023).
myopathy (4 papers, 2015 to 2024). A disease of the muscle in which the muscle fibers do not function properly. "The variant of NARS2 was first reported in two siblings with myopathy and combined complex I and IV deficiency in skeletal muscle." (PMID 38310242, 2024). "Severe myopathy was another characteristic clinical feature for cases with NARS2 variant." (PMID 38310242, 2024).
neurodevelopmental disorder (3 papers, 2023 to 2024). A behavioral and cognitive disorder with onset during the developmental period that involves impaired or aberrant development of intellectual, motor, or social functions. "As previous studies, neurodevelopmental disorders were the main features of NARS2 deficiency." (PMID 38310242, 2024).
cancer (2 papers, 2020 to 2025). A tumor composed of atypical neoplastic, often pleomorphic cells that invade other tissues. "Similarly, while NARS1 features widespread deletions in cancer genomes, NARS2 is mostly modified through gene amplifications." (PMID 33266490, 2020).
nervous system disorder (2 papers, 2022 to 2024). A non-neoplastic or neoplastic disorder that affects the brain, spinal cord, or peripheral nerves. "The results of this study improved our understanding of the phenotype and the variation spectrum of COXPD24 and indicated that compound heterozygous NARS2 mutations are involved in the pathogenesis of nervous system disorders." (PMID 36620461, 2022). "Compared to NARS1 mutations, NARS2 mutations are associated with earlier onset and worse condition of related nervous system diseases." (PMID 36620461, 2022).
neurodegenerative disease (1 paper, 2022). A disorder of the central nervous system characterized by gradual and progressive loss of neural tissue and neurologic function. "It includes the cytoplasmic type NARS1 and the mitochondrial type NARS2, both of which are associated with human neurodegenerative diseases." (PMID 36620461, 2022).
tumor (1 paper, 2024). "In this study, a novel nomogram was established by integrating the risk score of four genes (SCD, ALDH1A1, NARS2, and NFXL1), age, Gleason score, and tumor stage, each of which was an independent prognostic factor according to the multivariate Cox regression analysis." (PMID 39335669, 2024).
NARS2 also shares sentences with these, for which no sentence is quoted: Intellectual disability (4 papers); Hearing impairment (3); Perrault syndrome (2); sensorineural hearing loss (2); Autosomal recessive spastic ataxia with leukoencephalopathy (1); Cerebral atrophy (1); colorectal adenoma (1); Combined oxidative phosphorylation deficiency 24 (1); Dystonia (1); epilepsia partialis continua (1); Epileptic encephalopathy (1); infantile spasms (1); lactic acidosis (1); leukodystrophies (1); Leukoencephalopathy (1); microcephaly (1); Myoclonus (1); neonatal diabetes mellitus (1); Neurodevelopmental delay (1); nonsyndromic deafness (1); Onset (1); ovarian failure (1); ovarian serous cystadenocarcinoma (1); Progressive encephalopathy (1); skin cutaneous melanoma (1); Spastic paraplegia (1); Stroke (1); type 2 diabetes (1); viral infection (1).